MEIOC (meiosis specific with coiled-coil domain)
Description:
Is required for meiosis completion in both male and female germ cells. Confers stability to numerous meiotic mRNAs in gonads allowing proper initiation and progression into meiosis prophase I. The function may involve YTHDC2 and is independent of induction by retinoic acid (RA). Maintains an extended meiotic prophase I by properly promoting the transition from a mitotic to a meiotic cell cycle program by binding transcripts through its interaction with YTHDC2 that regulate the mitotic cell cycle.
Synonyms: C17orf104; FLJ35848
Tractability: No criterion of Open Targets' tractability assessment is met for any kind of drug.
Gene: Protein-coding gene on chromosome 17 (44,656,404 to 44,690,308, forward strand). Ensembl gene ENSG00000180336.
Subcellular location: Cytoplasm; Nucleus
Subcellular location (Human Protein Atlas): Cell Junctions
Gene Ontology:
Biological process: chromosome organization involved in meiotic cell cycle; female meiosis I; germline cell cycle switching, mitotic to meiotic cell cycle; male meiosis I; mRNA stabilization; oocyte development; spermatid development; double-strand break repair; meiotic cell cycle; metaphase chromosome alignment; spermatogenesis; synaptonemal complex assembly
Cellular component: cytoplasm; nucleus
Genetic constraint (gnomAD): Loss-of-function variants: 9 observed, 71.65 expected, observed/expected ratio (o/e) 0.13, 90% interval 0.075 to 0.22. The upper end of that interval is the gene's LOEUF score, 0.22, which puts it in group 1 of 6, group 1 being the genes least tolerant of losing a copy. Missense variants: 822 observed, 1,050.1 expected, observed/expected ratio (o/e) 0.78, 90% interval 0.74 to 0.83. Synonymous variants: 340 observed, 367.24 expected, observed/expected ratio (o/e) 0.93, 90% interval 0.85 to 1.01.
Homologues: Orthologues: chimpanzee MEIOC (99% identical), macaque MEIOC (97% identical), rabbit MEIOC (91% identical), dog MEIOC (89% identical), pig MEIOC (89% identical), rat Meioc (89% identical), mouse Meioc (89% identical), guinea pig MEIOC (79% identical), tropical clawed frog MEIOC (34% identical), zebrafish moto (26% identical).
Diseases named in the same sentence as MEIOC in open-access papers:
MEIOC is named in the same sentence as 4 diseases in open-access papers, as found by Europe PMC text mining. Sharing a sentence is not in itself a finding about the gene and the disease.
MEIOC shares sentences with these, for which no sentence is quoted: male infertility (1 paper); melanoma (1); ovarian tumor (1); tumor (1).